NES (nestin)
Diseases named in the same sentence as NES in open-access papers (continued):
Sharing a sentence is not in itself a finding about the gene and the disease.
glioma (continued). "Furthermore, the gliomas were found in the Nestin drive tv-a neural progenitors, but not in the differentiated GFAP-tv-a astrocytes, highlighting the importance of both cooperating mutations as well as the differentiation status of the cell of origin." (PMID 21896959, 2011). "Some studies have shown that nestin is a negative prognostic factor in terms of survival, while other studies, including ours, have not identified any statistically significant correlation between its reaction and the survival of patients with grade 4 glioma (either mutant IDH or wildtype)." (PMID 36136867, 2022). "The mRNA and protein expression levels of Nestin, SOX2, and Oct4 were markedly up-regulated in these stem-like cells/spheroids (P < 0.05), indicating their close similarity to GSCs and that bortezomib might inhibit the stemness of glioma cells in a dose-dependent manner." (PMID 31796105, 2019). "The IDH1 mutation impeded the maturation of astrocytes with low OGDH, but we found that it did not alter the expression of GFAP, Nestin, CD133, and CD44 in U87 and U251 glioma cells." (PMID 39872214, 2024). "We identified the integrin αvβ3/CDC42/F-actin/YAP-1/Nupr1/Nestin signaling pathway, which was independent of the PI3K/AKT signaling in 3D collagen/FN cultured glioma cells." (PMID 33408794, 2021). "We found that the delivery of CMV70-3P inhibitor significantly inhibited SOX2 expression in U118CMV infected and GBM13 glioma stem cells (p < 0.029 and 0.008) without altering the expressions of CD133, NESTIN and OLIG2." (PMID 27517625, 2017). "The mouse conditional knock-in models with mutant IDH1 induced in Nestin-expressing cells were reported to die directly after birth, while the analogous GFAP-induced models survived slightly longer, but did not develop gliomas during their lifespan." (PMID 27145078, 2016). "The lack of nestin/GFAP expression changes in human primary glioblastoma cells implicates no induction of cell differentiation by the treatments, although such responses have been described for 5-aza-dC in hypermethylated IDH1-mutant secondary gliomas." (PMID 31639020, 2019). "For example, expression of the γ134.5 gene under control of the nestin enhancer dramatically increased HSV replication in glioblastoma cell lines and primary glioma cells without increasing replication in astrocytes, but the nestin enhancer is highly active only in tumors of the nervous system." (PMID 30465046, 2018). "Indeed, we do not have complete evidence showing that in gliomas there is an intrinsically heterogeneous CSC-like population with a gradation of CD133, Nestin, and Sox2, but it appears to be plausible." (PMID 29518912, 2018). "The isolation and characterization of glioma CSCs is complicated by the absence of universal phenotypic markers, but a number of candidate proteins have been proposed for its role: СD133, CD44, CD49f, Musashi-1, Nestin, Nanog, Oct4 and Sox2." (PMID 31435515, 2018). "Immunofluorescence staining for nestin was negative, but immunofluorescence staining for GFAP was strongly positive, and β-tubulin staining was positive, indicating that glioma stem cells had differentiated." (PMID 28955297, 2017). "At present, a number of studies have shown that glioma stem cell markers CD133 and Nestin are closely related to the prognosis of patients with glioma, but some individual studies show that there is no clear relationship between CD133, Nestin and the prognosis of patients with glioma." (PMID 25967234, 2015).
glioblastoma (146 papers, 2004 to 2025). The most malignant astrocytic tumor (WHO grade IV). "Nestin, Nanog, Oct4 and Sox2 are genes implicated in the CSCs properties and are overexpressed in glioblastoma." (PMID 40688657, 2025). "In neuroblastoma and glioblastoma cells, for instance, Oxtr agonists differentially regulate the genes encoding Nestin and Map2." (PMID 28231043, 2017). "Another NSC key gene for stemness, Notch, has been implicated for some time in BTSC onset and maintenance; in fact, its activation in association with K-Ras increases in glioblastoma mice models the percentage of Nestin-positive cells, indicating its direct involvement." (PMID 37686355, 2023). "Furthermore, inferred chromosomal copy number alteration (CNA) analysis of hallmark genetic alterations in glioblastoma confirmed the Nestin/S100B and CD45− marker definition to capture the majority of malignant cells of patients in which these hallmark CNAs were detected." (PMID 39304781, 2024). "Resveratrol, a plant antitoxin, inhibits the growth, migration, invasion, and expression of nestin in glioblastoma cells." (PMID 40799240, 2025). "For instance, nestin is highly expressed in CSCs in glioblastoma, which play a crucial role in tumor initiation, maintenance, and resistance to therapy." (PMID 40799240, 2025). "successfully suppressed nestin expression using shRNA, which notably decelerated the growth of glioblastoma." (PMID 40799240, 2025). "Second, we utilized freshly-resected murine glioblastoma-like cells isolated from tumors induced by RCAS-PDGAB lentivirus injection into Nestin-Tva/Cdkn2a-/- mice." (PMID 39773984, 2025). "Clusters 1–3 represented glioblastoma cells expressing Nestin, Ki67, EGFR and VEGFA, with cluster 1 showing the most aggressive signature and highest inferred fraction of cells in the G2M cell cycle phase." (PMID 39304781, 2024). "To localize pTrk in Nestin+ glioblastoma tissue, we performed immunofluorescence labeling with anti-Nestin." (PMID 39039193, 2024). "Cell surface markers of glioblastoma stem‐like cells (Nestin, CD133, and OCT4) were positive for both GSC11 and GSC23 cells." (PMID 38332576, 2024). "For example, in glioblastoma and basal cell carcinoma models, Nestin-positive and Lgr5-positive cells were used as markers for QCCs that persist after chemotherapy." (PMID 39594777, 2024). "In the context of this study, single-cell profiling would make sense in Nestin-positive glioblastoma tissue with a high abundance of pTrk-kin at 90 kDa (immature Trk), or in the case of kinase-active NTRK-fusion proteins in a corresponding cancer biopsy." (PMID 39039193, 2024). "Our findings revealed elevated levels of Notch1, CD133, and Nestin expression in glioblastomas from the GFAP-Cre; KrasG12D; APCL/+; p53L/L mice when compared to brain sections from the GFAP-Cre;KrasG12D;p53L/L group." (PMID 38473403, 2024). "We recently showed a trend for reduced survival in patients with high levels of Nestin, a neural stem cell marker, in glioblastoma tumor samples." (PMID 39039193, 2024). "Accumulation of Nestin+ or CD133+ cells around glioblastoma vasculature was reported by one study that performed IHC and IF for these markers to assess transdifferentiation of GSCs to endothelial cells." (PMID 36823554, 2023). "Highly motile Nestin/IE1-positive cells were spotted leaving the core which are similar to the neural-progenitor-like tumor cells detected in glioblastoma, especially the ones adopting the Lévy-like movement patterns." (PMID 37147437, 2023). "It therefore seems more probable that additional factor(s) mediate lamin A/C turnover in response to nestin depletion in glioblastomas and possibly in other cell types." (PMID 37619289, 2023). "BTSC cellular markers have been studied for various reasons, one being the prognosis of glioblastoma; CD133 and high Nestin expression have been correlated with poor outcomes in glioblastoma patients." (PMID 37686355, 2023).
glioblastoma (continued). "In glioblastoma cells, nestin interacts with lamin A/C; when its expression is inhibited, lamin A/C protein levels rapidly diminish by a mechanism that involves poly-ubiquitination and proteasome activity." (PMID 37619289, 2023). "The detection of nestin in blood would be unsensitive and unspecific; indeed nestin is modified in neurological diseases involving neural cells activation and proliferation in central nervous, system such as glioblastoma." (PMID 35789864, 2022). "At the protein level, we also analysed the expression of LIF, two known stem cell markers, Nestin and SOX2, as well as cleaved NOTCH1, the expression of which has been linked to glioblastoma proliferation and stemness." (PMID 35203105, 2022). "Nestin, normally active during embryogenesis, is shut down in the adult brain but is active in glioblastoma cells." (PMID 35965554, 2022). "The GSC markers (SOX2, OCT4, CD9, CD133, and nestin) indicate the differentiation of glioblastoma cells into GSCs." (PMID 35054779, 2022). "Other strategies to rescue viral replication in attenuated Δγ134.5 oHSVs included the re-insertion of the γ134.5 gene under the nestin promoter (oHSV rQNestin34.5v.2) to prevent replication in differentiated neural cells and limit it to glioblastoma cells." (PMID 34578259, 2021). "The capability for neural differentiation in stable glioblastoma clones during GCV treatment was assessed by performing immunocytochemistry for nestin, GFAP, and βIII-tubulin." (PMID 34370752, 2021). "Overexpression of Emx2 under the Nes promoter (Nestin) suppressed cell proliferation in glioblastoma cell lines." (PMID 34016958, 2021). "Although the functional role of nestin in malignancy is poorly understood, a study in glioblastoma cell lines suggests a role for nestin in tumourigenesis." (PMID 32260145, 2020). "Such a chemotherapy-induced selection of nestin-positive cells has been reported in a glioblastoma model." (PMID 32903755, 2020). "In glioblastoma cells, Nestin regulates growth, stemness, and invasion through the alteration of HSC71 (gene HSPA8)." (PMID 32429463, 2020). "Another E3 ligase, TRIM11, also regulates EGFR levels and TRIM11 expression correlated closely with glioblastoma stem cell (GSC) markers Nestin and CD133 and promoted tumorsphere formation." (PMID 33324551, 2020). "The class VI intermediate filament nestin is also discussed as an overexpressed cancer stem cell marker in glioblastoma." (PMID 32260145, 2020). "Glioblastoma stem cells (here defined as CD133+Nestin+) have since been identified as a distinct subpopulation, critical to tumorigenesis." (PMID 33324551, 2020). "Many reports have showed that Nestin knockdown suppressed the proliferation, invasion, and migration of glioblastoma cells." (PMID 32429463, 2020). "Next, the co-expression of the glioblastoma stem cell marker NESTIN and NKG2DLs (MICA, MICB, ULBP1, ULBP2, ULBP3) in these suspended cell spheres was assessed by flow cytometry." (PMID 31288857, 2019). "The authors of this study also analyzed gene expression in the glioblastoma cohort of TCGA research network and found an association between HSP90 expression and stem cell markers such as CD133 and nestin, along with HIF target genes." (PMID 31752169, 2019). "The tumors derived from co-injecting GFP-N and I-Red cells exhibited aggressive glioblastoma characteristics including hemorrhaging, invasion, and necrosis, along with high expression of stem cell markers including Nestin, CD133, and GFP." (PMID 30804471, 2019). "Xenograft mouse model studies showed that 5-8F nasopharyngeal carcinoma cells, hepatocellular carcinoma cell line Huh7, and human glioblastoma cell line A172 expressing nestin shRNA yielded decreased tumor volume compared to those from control cells." (PMID 31126068, 2019).
glioblastoma (continued). "We describe novel murine immunocompetent glioblastoma stem cell (GSC) lines derived from Nestin-CreERT2 Quaking (QKI)L/L; P53L/L; PTENL/L (QPP) mice and determine their sensitivities to immunotherapies." (PMID 30400822, 2018). "Nestin expression was markedly different in glioblastoma (GBM) compared to the other tumour types, with high levels of expression outside the vasculature; as previously reported." (PMID 30279450, 2018). "Using patient derived fibroblasts (P0385) and primary glioblastoma cells (P0383) we were able to discriminate both types of cells using an antibody directed against nestin." (PMID 30123089, 2018). "Tlx transcripts were found to be overexpressed in human glioblastomas, where Tlx expression was restricted to a subpopulation of nestin-positive perivascular tumor cells." (PMID 30279357, 2018). "Glioblastoma stem cells rely on multiple key stemness-related proteins such as Nestin, CD133, SOX2, Olig2, BMI1, and ZEB138,39." (PMID 30022047, 2018). "Downregulation of the steady-state levels of Nestin and ZEB1 was observed supporting that AMG232 modulates stemness regulators linked to maintenance of the glioblastoma 3D growth." (PMID 30022047, 2018). "Though nestin has only been sparsely investigated in the context of hypoxia, these findings confirm previous studies carried out on both glioblastomas by our group and on cochlear stem cells." (PMID 29708435, 2018). "We also used double immunofluorescent staining to demonstrate the association between the expression of ObR and CD133, as well as Nestin, in glioblastoma tissues." (PMID 28938545, 2017). "The co-expression of ObR and CD133 or Nestin to constitute the channel indicated that ObR-positive glioblastoma cells displayed GSC properties." (PMID 28938545, 2017). "In our study, the expression of GSCs markers, CD133 and Nestin, has also been detected in glioblastoma tissues by immunohistochemistry." (PMID 28938545, 2017). "Double immunofluorescence stainings showed co-localization in the perivascular niches of Oct-4 and two other TSC markers CD133 and nestin in glioblastomas." (PMID 28030635, 2016). "Mer expression is also crucial for the maintaining primary glioblastoma-derived tumor spheres and increases expression of Nestin and Sox2 in a glioblastoma spheroid culture model." (PMID 27028863, 2016). "The cell growth kinetics, the expressions of glioblastoma TICs marker Nestin, the differentiation markers, GFAP and Tuj1, and the proliferation marker, Ki67 were very similar between the passage 1 and 10 glioblastoma TICs." (PMID 27549983, 2016). "It has been reported recently, that CD133 is only expressed in a subset of glioblastomas, while observation of abundant nestin expression is in complete agreement with several previous reports that came to the same conclusion." (PMID 24086629, 2013). "This study revealed that CD133+ glioblastoma cells expressed high levels of nestin but expressed low levels of GFAP and NSE." (PMID 23251243, 2013). "In CD133+ glioblastoma cells, the nestin-positive expression rate was 97.34±2.14%, GFAP was 1.44±0.27% and NSE was 1.35±0.24%." (PMID 23251243, 2013). "By contrast, CD133− glioblastoma cells expressed low levels of nestin (0.47±0.06%), but had high expression levels of GFAP (77.41±8.49%) and NSE." (PMID 23251243, 2013). "CD133+/Nestin+ cells isolated from glioblastoma, medulloblastoma, ependymomas, and oligodendrogliomas migrate to and interact tightly with the vascular tubes formed by endothelial cells." (PMID 22685459, 2012). "Intriguingly, thirty-six phosphorylation sites, including eleven novel sites, were identified regarding nestin, which is a well-known marker of glioblastoma stem cells." (PMID 22912867, 2012). "Its occurrence in tumor cells is not limited to the cytoplasm only; nestin localization in cell nuclei was clearly confirmed in some neuroblastoma and glioblastoma cell lines." (PMID 18925963, 2008).
glioblastoma (continued). "In human medulloblastoma, ependymoma, oligodendroglioma and glioblastoma, tumors with the highest concentrations of blood vessels exhibited the greatest number of Nestin+ cells." (PMID 17615543, 2007). "Our work focused on a detailed study of the nestin cytoskeleton in cell lines derived from glioblastoma multiforme, because re-expression of nestin together with down-regulation of GFAP has been previously reported in this type of brain tumor." (PMID 16457706, 2006). "This situation was reported in the U-373 MG glioblastoma cell line using the same monoclonal anti-nestin antibody as was used in our study; in these experiments, more details were described in the intermediate filament network after nestin detection." (PMID 16457706, 2006). "Using indirect immunofluorescence, we described the re-expression of nestin and the specific morphology of nestin-positive intermediate filaments in glioblastoma cells." (PMID 16457706, 2006). "A reduced GFAP-positivity in high-grade astrocytomas has been reported in several studies and experiments carried out on the U-373 MG glioblastoma cell line has confirmed a transcription level regulation of both nestin re-expression and GFAP down-regulation." (PMID 16457706, 2006). "Using epifluorescence and confocal microscopy, we described the morphology of nestin-positive intermediate filaments in glioblastoma cells of both primary cultures and the derived cell lines, as well as the reorganization of nestin during mitosis." (PMID 16457706, 2006). "Even using indirect immunofluorescence, a diffuse signal for nestin in the position of cell nucleus has also been identified in primary cultures of glioblastoma cells." (PMID 16457706, 2006). "Our study was focused on the detection and precise morphological characterization of the nestin cytoskeleton in two cell lines derived from glioblastoma multiforme." (PMID 16457706, 2006). "The aim of this study was to investigate, at both the cellular and ultrastructural levels, the nestin cytoskeleton in individual cells of two cell lines derived from glioblastoma multiforme." (PMID 16457706, 2006). "Differentiation of the neurospheres from one adult glioblastoma decreased nestin expression and increased that of glial and neuronal markers." (PMID 15469606, 2004). "In summary, this study demonstrated that All-Trans Retinoic Acid (ATRA) treatment significantly reduces the expression of the key stemness markers SOX2 and Nestin in the established glioblastoma cell lines U87-MG and A172, when cultured under neurosphere-promoting conditions." (PMID 40422249, 2025). "A large number of studies have shown that the overexpression of nestin can regulate the stemness to enhance proliferation and migration in glioblastoma, lung adenocarcinoma, colorectal cancer, pancreatic cancer, triple negative breast cancer and cervical cancer." (PMID 40799240, 2025). "Top NADs effectively reduced fractions of Nestin+ cells and metabolic activity in PDCs, total cell numbers in adherent cell lines (LN-229 and LN-308) and spheroid size in glioblastoma-initiating cell lines (ZH-161 and ZH-562), with confirmed concentration–response relationships." (PMID 39304781, 2024). "Specifically, the analysis of mRNAs-lncRNAs networks in glioblastoma tissue-derived CD133+/Nestin CSCs and their differentiated derivatives revealed three pairs of lncRNAs and their targeted mRNAs that may critically affect CSC differentiation." (PMID 36831395, 2023). "Furthermore, TCGA analysis reveals that IGFBP2 is up-regulated in classical glioblastoma, reputed for high Nestin expression." (PMID 36430641, 2022). "Further, we aimed to verify our in vitro findings in an orthotopic intracranial glioblastoma xenograft model and to analyze whether nuclear accumulation of Survivin in HGG patients’ tissue is the consequence of NES mutations." (PMID 34100981, 2021). "Inhibition of EZH2 led to down-regulation of nestin in glioblastoma." (PMID 32903755, 2020).